SSU72 (SSU72 homolog, RNA polymerase II CTD phosphatase)
Description:
Protein phosphatase that catalyzes the dephosphorylation of the C-terminal domain of RNA polymerase II. Plays a role in RNA processing and termination. Plays a role in pre-mRNA polyadenylation via its interaction with SYMPK.
Synonyms: HSPC182; PNAS-120
Tractability: PROTAC: ubiquitination databases record sites on it; its protein half-life has been measured; a small molecule that binds it is known.
Target class: Serine protein phosphatase; Protein Phosphatase; Phosphatase; Enzyme
Gene: Protein-coding gene on chromosome 1 (1,541,673 to 1,574,884, reverse strand). Ensembl gene ENSG00000160075.
Subcellular location: Nucleus; Cytoplasm
Subcellular location (Human Protein Atlas): Cytosol; Nucleoplasm
Pathways (Reactome):
Gene expression (Transcription): RNA polymerase II transcribes snRNA genes
Gene Ontology:
Molecular function: protein binding; protein serine/threonine phosphatase activity; RNA polymerase II CTD heptapeptide repeat phosphatase activity; phosphoprotein phosphatase activity; protein tyrosine phosphatase activity
Biological process: co-transcriptional mRNA 3'-end processing, cleavage and polyadenylation pathway; termination of RNA polymerase II transcription; mRNA 3'-end processing; mRNA processing; regulation of transcription by RNA polymerase II
Cellular component: mRNA cleavage and polyadenylation specificity factor complex; cytoplasm; nucleus
Genetic constraint (gnomAD): Loss-of-function variants: 10 observed, 20.55 expected, observed/expected ratio (o/e) 0.49, 90% interval 0.3 to 0.82. The upper end of that interval is the gene's LOEUF score, 0.82, which puts it in group 3 of 6, group 1 being the genes least tolerant of losing a copy. Missense variants: 151 observed, 243.77 expected, observed/expected ratio (o/e) 0.62, 90% interval 0.54 to 0.71. Synonymous variants: 116 observed, 96.91 expected, observed/expected ratio (o/e) 1.2, 90% interval 1.03 to 1.4.
Homologues: Orthologues: guinea pig SSU72 (99% identical), mouse Ssu72 (99% identical), tropical clawed frog ssu72 (93% identical), chimpanzee SSU72 (90% identical), zebrafish ssu72 (89% identical), dog SSU72 (83% identical), rat Ssu72 (83% identical), Drosophila melanogaster Ssu72 (61% identical), Caenorhabditis elegans ssup-72 (57% identical). Paralogues in human: SSU72L3 (72% identical), SSU72L2 (71% identical), SSU72L4 (71% identical), SSU72L1 (71% identical), SSU72L5 (71% identical), SSU72L6 (70% identical).
Diseases named in the same sentence as SSU72 in open-access papers:
SSU72 is named in the same sentence as 12 diseases in open-access papers, as found by Europe PMC text mining. Sharing a sentence is not in itself a finding about the gene and the disease. The quoted sentences say what the papers report.
autoimmune disease (3 papers, 2017 to 2024). A disorder resulting from loss of function or tissue destruction of an organ or multiple organs, arising from humoral or cellular immune responses of the individual to their own tissue constituents. "Uncovering the possible therapeutic implications of targeting Ssu72 in autoimmune disease merits further exploration as well." (PMID 38304578, 2024). "Our findings provide the first evidence showing that Ssu72 overexpression may attenuate autoimmune disease in an animal model." (PMID 28710354, 2017). "Thus, it is possible to treat autoimmune diseases by regulating Ssu72 phosphatase activity." (PMID 33917542, 2021). "We have discussed how newly discovered physiological functions of Ssu72, a phosphatase, could influence the pathogenesis of diverse diseases including NAFLD and autoimmune diseases." (PMID 33917542, 2021). "We hypothesized that Ssu72 suppresses STAT3 activation and is a critical and highly conserved protein involved in autoimmune diseases." (PMID 28710354, 2017).
hepatocellular carcinoma (3 papers, 2021 to 2024). A malignant tumor that arises from hepatocytes. "The downregulation of Ssu72 is highly conducive to the development of NAFLD/NASH-associated hepatocellular carcinoma (HCC)." (PMID 33917542, 2021). "Inactivation of Ssu72 is also linked to hepatocellular carcinoma (HCC)." (PMID 38304578, 2024). "Hepatic carcinoma may be due to dysregulation of Rb in liver cells in the absence of Ssu72." (PMID 38304578, 2024).
non-alcoholic fatty liver disease (2 papers, 2023 to 2024). "Investigation into the role of Ssu72 in thermogenic tolerance may pave the way for discovery of a treatment for metabolic diseases like obesity related diseases and non-alcoholic fatty liver disease." (PMID 38304578, 2024). "In this context, our study raises the strong possibility that Ssu72 is a potential therapeutic target for several metabolic diseases including obesity-related diseases and non-alcoholic fatty liver disease (NAFLD)." (PMID 36841836, 2023).
viral disease (2 papers, 2022 to 2024). "Since Ssu72 is not required for transcription of all host genes, but is crucial for HIV-1 propagation, it is a potential target for finding an efficient treatment for the viral disease." (PMID 38304578, 2024).
Arthritis (1 paper, 2017). Inflammation of a joint. "Administration of the Ssu72 overexpression vector attenuated the severity of arthritis, as indicated by the decrease in the mean arthritis score and amelioration of arthritic tissue pathology in the affected joints, as revealed by histological approaches." (PMID 28710354, 2017).
liver diseases (1 paper, 2021). "Eventually, the depletion of Ssu72 can result in mononucleated polyploid hepatocytes through excessive endoreplication cycles, inducing liver diseases including non-alcoholic fatty liver disease (NAFLD), fibrosis, and steatohepatitis (NASH) in a mouse model." (PMID 33917542, 2021). "Additionally, the depletion of Ssu72 contributes to hepatic disorders, including necrosis, steatohepatitis, and fibrosis, via aberrant hepatic chromosome polyploidization." (PMID 33917542, 2021).
infection (5 papers, 2019 to 2023). The state of being infected such as from the introduction of a foreign agent such as serum, vaccine, antigenic substance or organism. "The Ssu72 deletion was induced by infection with a Cre recombinase adenovirus (Ad-Cre) or by intercrossing with albumin-Cre (Alb-Cre; a liver-specific Cre) mice." (PMID 34987641, 2022). "Infection of ESf/f, MEFf/f, and hepatocytef/f with Ad-Cre resulted in an efficient reduction of Ssu72." (PMID 34987641, 2022). "Here, seeds infection assays showed that deletion of ssu72 resulted in a severe defect in pathogenicity on maize and peanuts, which is consistent with the previous finding in F. graminearum." (PMID 33202955, 2020). "Notably, seeds infection assays indicated that phosphatase Ssu72 is crucial for pathogenicity of A. flavus." (PMID 33202955, 2020). "Our results suggest that AIVs infection induce TRT by reducing SSU72 expression, thereby impairing host immune responses, a molecular mechanism acting through the NS1-SSU72-trans-TRT-STAT1/2 axis." (PMID 35332300, 2022). "However, the role of phosphatase Ssu72 in seeds infection is still unknown in A. flavus." (PMID 33202955, 2020). "We downregulated SSU72 levels using two specific shRNAs and collected HT1080 cells for analysis of telomere length 6 weeks after infection." (PMID 30796050, 2019). "In addition, the analysis revealed that some of these proteins had been previously associated to SARS-CoV-2 early (FKBP2; UBXN1; PPP1R11), middle (UBXN1; PPP1R11; CAPN5) and late-stage infection in human male blood (FKBP2; UBXN1; PPP1R11; SURF4; SSU72)." (PMID 37063416, 2023).
metabolic disease (2 papers, 2023 to 2024). A congenital disorder (due to inherited enzyme abnormality) or acquired (due to failure of a metabolically important organ) disorder resulting from an abnormal metabolic process. "Although some evidence for the role of Ssu72 in the pathogenesis of metabolic diseases has been found, its functions in major metabolic tissues such as adipose tissue are still largely unknown." (PMID 36841836, 2023).
SSU72 also shares sentences with these, for which no sentence is quoted: diabetes (1 paper); Insulin resistance (1); liver fibrosis (1); Type 2 Diabetes (1).